ASIC3 (acid sensing ion channel subunit 3)
Diseases named in the same sentence as ASIC3 in open-access papers (continued):
Sharing a sentence is not in itself a finding about the gene and the disease.
ASIC3 also shares sentences with these, for which no sentence is quoted: Acidosis (3 papers); Hypertension (3); epilepsy (2); generalized tonic clonic seizure (2); intervertebral disc degeneration (2); myocardial infarct (2); Pseudomonas infection (2); adenocarcinoma (1); behavioural disorders (1); colorectal cancer (1); Constipation (1); deafness (1); Dry skin (1); dyspepsia (1); gastrointestinal disorders (1); Gliosis (1); Hyperreflexia (1); infectious disease (1); interstitial cystitis (1); irritable bowel syndrome (1); melanoma (1); metastatic melanoma (1); peripheral artery disease (1); peripheral neuropathy (1); postherpetic neuralgia (1); rhabdomyolysis (1); Skin ulcer (1); Splenomegaly (1); ulceration (1); virus infection (1).